IL2 (interleukin 2)
Diseases named in the same sentence as IL2 in open-access papers (continued):
Sharing a sentence is not in itself a finding about the gene and the disease.
cancer (continued). "Th17 cells are polyfunctional in cancer, secreting IL-2, tumor necrosis factor, and IFN-γ." (PMID 32104586, 2020). "However, some cancer studies reported decreased γδ T cell responses during extended bisphosphonate/IL-2 therapy regimens due to the development of anergy." (PMID 33348583, 2020). "The combinations of cytokine and ACT are currently being evaluated in multiple clinical trials in a variety of cancer types, including with different doses of IL-2 (NCT02414945, NCT04052334) or using IL-15 and IL-2 as an adjuvant for NK cell infusion (NCT03669172, NCT03213964)." (PMID 33266177, 2020). "Consequently, the IL-2 therapy is still reserved for a few forms of cancer like metastatic renal cell carcinoma and intralesional application to treat metastatic melanoma." (PMID 33027905, 2020). "Notably, multifunctional CD4+ and CD8+ T cells capable of producing multiple Th1 cytokines (IFN-γ, TNF-α, IL-2) and expressing the degranulation marker (CD107a) play a critical role in cancer protection." (PMID 33105813, 2020). "Therefore, we investigated if our IL-2/IL-15-expanded Vγ9Vδ2 T cells were also capable of improved cancer cell killing." (PMID 32983105, 2020). "IL-2 is also the first cytokine approved by the FDA to be used in cancer treatment." (PMID 33266177, 2020). "Indeed, to date, only IFNα and IL‐2 have found limited clinical use for the treatment of human cancer due to a narrow therapeutic window." (PMID 31912630, 2020). "The systemic inflammatory response from cancer cells promotes the infiltration of neutrophils, which benefits cancer progression via secreting interleukin-2 (IL-2), interleukin-6 (IL-6), interleukin-10 (IL-10), tumor necrosis factor α (TNF-α) and vascular endothelia growth factor (VEGF)." (PMID 32510138, 2020). "More importantly, other than cancer signaling pathways, immune processes such as IL-2 and IL-6 signaling pathways, INF-α and INF-γ response, and complement activity were dominantly associated with TBX22low status (14 terms were significant GSEA results, 13 were immune- or cancer-related processes)." (PMID 33392186, 2020). "Regarding toxicity, the combined therapeutic use of bisphosphonate and IL-2 has been used with modest success in cancer patients to promote the in vivo expansion of γδ T cells, with relatively minor adverse effects, including fever, injection site soreness, nausea, and diarrhea, being reported." (PMID 33348583, 2020). "In order to optimize anti-cancer activity viruses are engineered to express various immuno-stimulatory transgenes, most prominently T cell and DC activating cytokines like interleukin-2 (IL-2), interleukin-15 (IL-15) or GM-CSF91." (PMID 32542113, 2020). "In addition, HD IL-2 can expand potently suppressive CD4+CD25+ Foxp3+ Tregs in cancer patients, possibly limiting its efficacy." (PMID 32005826, 2020). "Cytokines are small proteins that are essential in shaping protective antitumor immune responses, however, the utility of cytokines in the clinic for cancer immunotherapy is limited, with only TNFα, IFNα, and recombinant IL-2 approved for a small number of cancer indications." (PMID 32457754, 2020). "Therefore, we tested a unique cancer treatment strategy comprised of oral delivery of Saltikva, an attenuated strain of Salmonella typhimurium that contain the human gene for interleukin-2." (PMID 32554977, 2020). "Nevertheless, many occurring adverse events support the hypothesis that not only cancer cells are affected by IL-2 impact." (PMID 33027905, 2020). "Modified interleukin-2 (IL-2) formulations are being tested in cancer patients." (PMID 33353953, 2020). "Certain pro-inflammatory cytokines (e.g., interleukin-2) may provide a complementary anti-cancer activity and may be ideal combination partners, in addition not only to immune checkpoint inhibitors, but also to radiation and cytotoxic agents." (PMID 33110477, 2020).
cancer (continued). "High doses of IL-2 are often used to treat malignant tumors, because IL-2 preferentially induces activation and proliferation of effector T cells (Teff cells), NK cells, and other cells; however, the effectiveness of this treatment is limited by toxicity and instability." (PMID 33013198, 2020). "A recent study has suggested that CD11b+Gr1+ MDSCs produced during cancers might inhibit IL-2 production through nitration of lck." (PMID 32269573, 2020). "The modest accumulation of IL2 at the site of disease and its short half-life represent additional limitations for a broader applicability of this immunostimulatory agent in cancer treatment." (PMID 33216834, 2020). "PD-1/PD-L1 binding has been demonstrated to block the effector function and motility of most lymphocytes, thereby decreasing the production of IL-2 (interleukin-2) by helper T-cells and diminishing the clonal proliferation of cytotoxic T-cells in response to cancer cells." (PMID 31530839, 2019). "Therefore, this next-generation IL-2 reduces toxicity while increasing TILs that potentiate combined cancer therapies." (PMID 31462678, 2019). "IFN-γ and IL-2 are important inflammatory cytokines, especially against cancer." (PMID 31649244, 2019). "Since then, IL-2 has been considered the first effective immunotherapy for human cancer." (PMID 30987001, 2019). "The role of IL-2 in cancer immunotherapy has become a matter of intense debate." (PMID 31195686, 2019). "The use of cytokines from the IL-2 family (also known as the common gamma chain cytokine family) such as IL-2, IL-7, IL-15 and IL-21 to activate the immune system of cancer patients is currently the one of the most important fields of cancer immunotherapy research." (PMID 31703694, 2019). "In in vitro studies, trastuzumab and pertuzumab increased the cytotoxic level of IL-2 activated NK cells targeting ERBB2 positive cancer cell lines, and an anti-programmed cell death-ligand 1 (PD-L1) antibody avelumab increased ADCC by NK cells targeting triple negative breast cancer cells." (PMID 31614472, 2019). "NK-92MI cells can secrete sufficient quantities of bioactive IL-2, a pivotal cytokine which has proved to be able to activate NK-lymphocytes and enhance immunity against cancer as well as to proliferate and mediate the antitumor effects in the absence of exogenous IL-2." (PMID 31057396, 2019). "Also, anti-cancer agents, including IL-2 + imatinib mesylate (three studies) and anti-CD22 monoclinal antibodies (mAb) (four studies), showed a dose-dependent increase in the incidence of CLS." (PMID 30691103, 2019). "If fully activated CTLs can be induced to secrete functional exosomes in humans in ways similar to mice, these functional exosomes could be injected together with IL-2 to boost low-affinity CTLs in immunotherapy for chronic infections and cancers." (PMID 31275303, 2019). "Since cancer cells have active DNA repair capacity, it is possible to speculate that this transient growth inhibition induced by IL-2 facilitates DNA damage repair, enabling cellular recovery, thereby increasing cell viability." (PMID 31662754, 2019). "However, a four-fold decrease in IL-2 was observed when E.G7 cancer cells were added to the OVA323-presenting DC and OT-II TCH co-culture." (PMID 31602007, 2019). "Likewise, anti-cancer agents, including IL-2 + imatinib mesylate (three studies) and anti-CD22 mAb (four studies) showed a dose-dependent increase in the incidence of CLS." (PMID 30691103, 2019). "Also, CD25 lost within activated T cells might be induced by competition for IL-2 between activated and regulatory T cells expressing higher levels of Foxp3, which has been directly associated with their potential to suppress the activation of effector T cells and correlated with cancer progression." (PMID 31616626, 2019).
cancer (continued). "Based on recent studies about the role of the immune system in malignancies, immunotherapies including immune modulators such as interleukin-2 and muramyl tripeptide, dendritic cells, immune checkpoint inhibitors, and engineered T cells have been utilized in patients with malignancies." (PMID 30693030, 2019). "Before treatment, the serum SA level of patients with oral malignant tumor was significantly higher than those of the control group and healthy group, while the IL-2 level was significantly lower than those of the other two groups, and the differences were statistically significant (P<0.05)." (PMID 31489003, 2019). "Currently, IL-2 is the only γc cytokine to be FDA-approved to treat patients with cancer." (PMID 30842774, 2019). "Further studies are needed to explore the dual effect of IL-2 in cancer therapy." (PMID 29854806, 2018). "The potential of IL-2 in expanding T cells without loss of functionality has led to its early use in cancer immunotherapy." (PMID 29854806, 2018). "Although this study provided evidence for IL-2 as potential treatment in autoimmune settings, this highly interesting finding was never followed up, likely due to the severe side effects of IL-2 observed in cancer immunotherapy." (PMID 29670626, 2018). "Therefore, we believe that FSD13 has great potential for clinical application to treat various cancers since it avoids the main disadvantages of IL-2 based immunotherapy." (PMID 30250191, 2018). "Benefits of IL-2 in cancer patients are limited by toxicity." (PMID 30400835, 2018). "The concept of adoptive immunotherapy (AIT) for cancer treatment was presented by Mule et al22 in the form of IL‐2 generated lymphokine‐activated killer (LAK) cells combined with repeated injections of recombinant IL‐2." (PMID 30003192, 2018). "However, more and more clinical studies found that high-dose IL-2 has a poor safety profile but a robust efficacy in only a fraction of patients with a restricted set of cancers." (PMID 29527328, 2018). "Not only is the use of IL-2 a remarkable manipulation of the host’s immune system resulting in eradication of the invading cancer, but it has also demonstrated one of the most durable long-term responses in cancer treatment." (PMID 29644213, 2018). "IL2 can reactivate these quiescent immune cells and stimulate them to destroy the cancer cells." (PMID 29467958, 2018). "Interleukin-2 (IL-2) is an important immunotherapy cytokine for various diseases including cancer." (PMID 29980186, 2018). "Noteworthy, in the cancer setting, low efficacy of high-dose IL-2 administration can be explained in part by the unwanted effect of IL-2 on Tregs, which constitutively express the high affinity IL-2 receptor [composed by three subunits: IL-2-Rα (CD25), IL-2Rβ and IL-2Rγ]." (PMID 29593717, 2018). "The present review discusses the prospects of IL-2 in immunotherapy for cancer." (PMID 29854806, 2018). "However, the associations of several other cytokines (IL-36γ, MIP-1β, RANTES, IP-10, IL-2, IL-4, Flt-3L, sCD40L) with cancer were dependent on the VMB composition." (PMID 29765068, 2018). "Similar to cancer settings, chronic filarial infection with continuous release of parasite antigens is associated with a lack of CD4+ T cell proliferation and production of IFN-γ and IL-2." (PMID 29668679, 2018). "A study on mice with cancer under treatment with cisplatin demonstrated that HemoHim could increase the activity of natural killer cells and Tc cells as well as the IL-2 and IFN-gamma secretion from splenocytes." (PMID 28975109, 2017).
cancer (continued). "Previously, several studies demonstrated that quercetin inhibited inflammation, enhanced immune function and promoted apoptosis by modulating key pathways regulating cancer, such as, prostaglandin G/H synthase 2, interleukin (IL)-2, peroxisome proliferator activated receptor gamma and caspase-9." (PMID 28099904, 2017). "Interestingly, immunotherapy with high-dose interleukin IL-2 has been reported to give rise to systemic autophagic syndrome, but is able to produce long-term remission in certain groups of cancer patients." (PMID 28629173, 2017). "The current study was performed to assess whether the concentration of ketamine, as adjuvant analgesics for patient with refractory cancer pain, was related to its effect on T cells interleukin-2 (IL-2)/interferon-γ (IFN-γ) expression in vitro." (PMID 28422864, 2017). "In addition, cancer cells pretreated with IFN-γ obviously inhibited IL-2 secretion by Jurkat T cells." (PMID 28404966, 2017). "T cells expanded by RNA electroporation of OKT3-28BB are phenotypically and functionally similar to OKT3/IL-2 T cells and may be considered an alternative for treating cancers when local T cell administration is required." (PMID 28523432, 2017). "Interleukin-2 (IL-2) is a T-cell proliferating factor used for cancer immunotherapy." (PMID 28497796, 2017). "Interleukin-2 (IL-2) is an established therapeutic agent used for cancer immunotherapy." (PMID 28497796, 2017). "Moreover, we identify the depletion of Tregs, rather than the expansion of cytotoxic CD8+ T-cells and NK cells, as a major determinant for antitumour activity, providing important guidance for the future development of IL-2 reagents for cancer immunotherapy." (PMID 28497796, 2017). "Similarly, IL-2 is also used in clinical trial to deliver significant benefit in the case of certain cancers and infectious diseases, including HIV." (PMID 28448542, 2017). "Moreover, IL-2 administration has been shown to also increase the percentage of circulating regulatory T cells in cancer patients, thus contributing to the inhibitory effects on NK cell cytotoxicity." (PMID 28668076, 2017). "Modeling IL-2 pathophysiology in HIS mice offers a means to understand the functions of effector and regulatory T cells in immune-mediated toxicities associated with cancer immunotherapy." (PMID 29176694, 2017). "The effects of melatonin in cancer were due to its ability to eliminate reactive oxygen species, which are messengers for cancer cell division and the amplification of the antitumor activity of IL-2." (PMID 28422058, 2017). "Similarities and differences between IL-2 and IL-15 effects on NK cells have been extensively reviewed elsewhere, and IL-15 might be the preferable cytokine for cancer therapy as it inhibits activation-induced cell death and it is considered safe." (PMID 28491060, 2017). "If these modifications also lower the toxicity of IL-2, which may be partly mediated by IL-2Rα, these IL-2-based compounds may make a comeback in cancer immunotherapy, including as vaccine adjuvants." (PMID 27660710, 2016). "IL-15 is of interest as it is closely related to IL-2 and has got the top position in the US National Cancer Institute’s ranking of 20 immunotherapeutic drugs with the greatest potential for broad usage in cancer therapy." (PMID 27686372, 2016). "An overall defect in the function of the immune system in cancer patients is another mechanism that may reduce the efficacy of IL-2 therapy." (PMID 27153543, 2016). "Evidence that supports the use of IL-2 administration in cancer treatment has been reported." (PMID 27293315, 2016). "Moreover, interleukin 2 was observed to enhance both cytotoxic mechanisms by promoting target recognition by NK cell and increasing NK-cancer cell interaction frequency." (PMID 27323411, 2016). "IL-2 has been used to treat cancer in patients since the 1980 s48." (PMID 27886209, 2016). "IL-2 is a pleiotropic cytokine with a multitude of target cells including cancer cells." (PMID 27293315, 2016).
cancer (continued). "An important question in the context of cancer immunotherapy is whether IL-15, as compared to IL-2, can boost γδ T cell effector functions, in terms of cytokine secretion and cytotoxic capacity." (PMID 27686372, 2016). "The circulating CD56dimCD16+ cells may also be altered and impaired in the subsequent activation by IL-2, and lose killing virus-infected and cancer cells." (PMID 27027597, 2016). "Furthermore, it has been demonstrated that cyclic mechanical strain applied in concert with interleukin-2 (IL-2) increased the fluidic leakage through the membrane, reproducing drug toxicity–induced edema typical of cancer patients treated with this molecule." (PMID 30404405, 2016). "Since IL-2- and IL-15- pre-activated NK cells may be used in protocols of adoptive immunotherapy in cancer patients, we further investigated the effect of BRAF-i and MEK-i on NK cells that had been pre-activated for 2 days with IL-2 or IL-15." (PMID 27563819, 2016). "IL-15 has been proposed as an alternative to the use of IL-2 in cancer therapy." (PMID 27356750, 2016). "IL-15, has been proposed as a promising candidate to replace IL-2 for cancer therapy." (PMID 27356750, 2016). "We speculated that the prolonged contact of CD103+ CD8+ TIL with the cancer islets might render these cells less fit to expand on IL-2." (PMID 27650547, 2016). "The danger molecule Hsp70 in the presence of pro-inflammatory cytokines, such as IL-2, might support the immune system to reinforce immunity against cancer." (PMID 26579130, 2015). "Additionally, earlier studies of nebulized IL-2 liposomes demonstrated regression of pulmonary metastases and increased bronchial lymphocyte and lytic effector cell activity in dogs with cancer." (PMID 26091536, 2015). "In the past, immunomodulatory agents such as interferon, interleukin-2, and liposomal-muramyl tripeptide phosphatidyl-ethanolamine have been tried, with some activity seen in subsets of patients; additionally, various cancer vaccines have been studied with possible benefit." (PMID 26301204, 2015). "The administration of high-dose IL-2 requires a monitored setting and possible transfer to an intensive care unit, a potential disadvantage to hospital management, as it requires more resources than routine cancer treatment." (PMID 26557408, 2015). "Since Tregs depend on exogenous IL-2 for survival, a suggested approach has been to use low-dose IL-2, which lacks the toxicity and immunostimulatory effects of the higher IL-2 doses used to treat cancer patients." (PMID 26379673, 2015). "IL-2 is a potent cytokine that is also proven to boost the immune system to fight cancer." (PMID 26255627, 2015). "Though cancer immunotherapy approaches have been pursued for decades and have been successful in some cases (e.g. IL-2 in melanoma), checkpoint inhibition and, in particular, PD-1/PD-L1 blockade, is the first strategy that is poised to impact the outcome in cancer patients on a broader scale." (PMID 25682878, 2015). "It has been described that treatment with IL-2 may increase the amount of regulatory T cells in cancer patients, while IL-7 may have opposite effects." (PMID 25972868, 2015). "Immunotherapy has also been applied for MEL therapy; immunotherapy employs cytokines that stimulate the patient's immune system to fight cancer, such as interleukin (IL), IL-2, IL-5, IL-7, and IL-21, interferon-α (INF-α), and granulocyte macrophage colony–stimulating factor (GM-CSF)." (PMID 26078967, 2015). "Given the inherently pro-thrombotic state of many cancer patients, it is theoretically possible that IL-2 therapy may have thrombotic complications, which indeed have previously been reported." (PMID 24884532, 2014). "IL-15 lacks this duality and may be a more promising anti-cancer agent than IL-2, especially if its stability and potency are enhanced by recombinant combination with IL-15Rα." (PMID 24276591, 2014).